KRTAP2-1 (keratin associated protein 2-1)
Description:
In the hair cortex, hair keratin intermediate filaments are embedded in an interfilamentous matrix, consisting of hair keratin-associated proteins (KRTAP), which are essential for the formation of a rigid and resistant hair shaft through their extensive disulfide bond cross-linking with abundant cysteine residues of hair keratins. The matrix proteins include the high-sulfur and high-glycine-tyrosine keratins (By similarity).
Synonyms: KRTAP2.1A; KAP2.1A
Tractability: No criterion of Open Targets' tractability assessment is met for any kind of drug.
Gene: Protein-coding gene on chromosome 17 (41,046,541 to 41,047,316, reverse strand). Ensembl gene ENSG00000212725.
Pathways (Reactome):
Developmental Biology: Keratinization
Gene Ontology:
Cellular component: cytosol; keratin filament
Genetic constraint (gnomAD): Loss-of-function variants: 2 observed, 1.48 expected, observed/expected ratio (o/e) 1.35, 90% interval 0.44 to 1.92. That is too few expected variants to judge how well the gene tolerates losing a copy. Missense variants: 13 observed, 39.83 expected, observed/expected ratio (o/e) 0.33, 90% interval 0.21 to 0.52. Synonymous variants: 6 observed, 17.98 expected, observed/expected ratio (o/e) 0.33, 90% interval 0.18 to 0.66.
Homologues: Orthologues: chimpanzee KRTAP2-1 (98% identical), mouse Krtap5-24 (43% identical), mouse Krtap5-26 (38% identical), mouse Krtap5-2 (36% identical), rat Krtap5-8 (35% identical), rat AABR07006049.1 (34% identical), mouse Krtap5-20 (33% identical). Paralogues in human: KRTAP2-3 (99% identical), KRTAP2-4 (99% identical), KRTAP2-2 (96% identical), KRTAP4-12 (52% identical), KRTAP4-6 (52% identical), KRTAP4-3 (51% identical), KRTAP4-11 (50% identical), KRTAP4-5 (50% identical), KRTAP4-9 (48% identical), KRTAP4-4 (46% identical), KRTAP9-1 (46% identical), KRTAP10-11 (45% identical), and 35 more.